GBA1LP (glucosylceramidase beta 1 like, pseudogene )
Synonyms: GBAP; GBAP1
Gene: Long non-coding RNA gene on chromosome 1 (155,210,695 to 155,228,027, reverse strand). Ensembl gene ENSG00000291137.
Diseases named in the same sentence as GBA1LP in open-access papers:
GBA1LP is named in the same sentence as 1 disease in open-access papers, as found by Europe PMC text mining. Sharing a sentence is not in itself a finding about the gene and the disease.
GBA1LP shares sentences with these, for which no sentence is quoted: Gaucher disease (1 paper).